CRP (C-reactive protein)
Diseases named in the same sentence as CRP in open-access papers (continued):
Sharing a sentence is not in itself a finding about the gene and the disease.
neurodegenerative disease (continued). "A causal relationship between CRP levels and neurodegenerative diseases was not proven by any of the studies." (PMID 38891863, 2024). "Fourth, the CRP levels might be increased in patients with chronic inflammatory diseases and neurodegenerative diseases." (PMID 32220241, 2020). "CRP might be related to cytokine activation and chronic inflammation, which are known to play a role in the progression of neurodegenerative diseases." (PMID 31727165, 2019). "This review considers current evidence supporting a mechanistic link between mCRP/CRP/IL-6 signaling and the amplification of stress and pain sensitivity, contributing to a broader understanding of how systemic inflammation may drive vulnerability to neurodegenerative disease." (PMID 41373439, 2025). "The WBC count, NLR, ESR, and CRP level are nonspecific biomarkers of systemic inflammation that can be elevated in infectious, autoimmune, or neurodegenerative diseases where the innate or adaptive immune systems are dysregulated." (PMID 38775192, 2024). "These biomarkers include glycated hemoglobin (HbA1c), C-reactive protein (CRP), erythropoietin (EPO), interleukin-6, uric acid, endocan, copeptin, and numerous other molecules involved in the pathogenesis of neurodegenerative diseases, lipid, and vascular metabolic pathways." (PMID 37371460, 2023). "A greater challenge is posed because the CRP value alone is not always helpful to distinguish between vertebral osteomyelitis and degenerative diseases of the spine." (PMID 31727136, 2019). "Since the majority of studies on neuroinflammation in patients with neurodegenerative diseases have been conducted on peripheral blood samples rather than CSF, our results on CRP in CSF could potentially bring us closer to the core of ALS pathophysiology." (PMID 32041109, 2020). "There was no study that evaluated the serum levels of CRP and the development of MCI or any other neurodegenerative disease in the IBD population." (PMID 38891863, 2024).
neurological diseases (54 papers, 2005 to 2026). "In the present study, 30-day mortality was associated with high CRP levels, low platelet count, and neurologic diseases." (PMID 29954339, 2018). "For example, in one study investigating the diagnostic utility of D-dimer and CRP concentration both in blood and cerebrospinal fluid (CSF) in neurological diseases, the authors reported high CSF D-dimer and CRP concentrations only in dogs with inflammatory conditions." (PMID 39330787, 2024). "The causal effect of CRP on neurological diseases may also be attributed to the shared genetic risk as the genetic correlation showed." (PMID 34386016, 2021). "They attenuate inflammation-induced disorders such as cardiovascular and neurological disorders via down-regulating pro-inflammatory cytokines (IL-6, CRP, COX-2, LPO, TGF-β1, NF-κB, and TNF-α), and pathways (IRAK4, MAPK, JAK/STAT3, TLR4, and ERK)." (PMID 41640995, 2026). "sNfL levels are often regarded as “the neurologist’s C-reactive protein,” reflecting activity in certain nervous system diseases." (PMID 38308244, 2024). "Meta-analysis was performed to examine the effect of Lf supplementation on CRP in adults (n = 3 trials, n = 208 subjects), including trials in healthy older females, T2D, and bedridden subjects with neurological disease." (PMID 35481594, 2022). "Elevated blood glucose and CRP (C-reactive protein) are usually related to a worsened clinical outcome in neurological diseases." (PMID 35677334, 2022). "Multivariate analysis showed that 30-day mortality was significantly lower in the other neurologic disease group and higher in patients with platelet count < 100,000/μL, and C-reactive protein (CRP) ≥ 5 mg/dL." (PMID 29954339, 2018). "Urinary CRP concentrations were significantly higher in dogs with micturition dysfunction (p = 0.0009) and in dogs with different neurological diseases (p = 0.0020) compared to the control group." (PMID 26746899, 2016). "Changes in the levels of inflammatory biomarkers, such as cytokines and C-reactive protein, may signal the early stages of neurological disorder development." (PMID 40872604, 2025). "Neuroinflammation is a key component of various neurological diseases and the levels of most central and peripheral pro-inflammatory markers, such as C-reactive protein and tumor necrosis factor α (TNFα), are increased in depressed patients and decrease to normal levels after recovery." (PMID 35449567, 2022). "This could make the field use of PCT assays, usually regarded as less sensitive/more specific than CRP, more debatable for the clinical scenario under study (initial assessment of neurological disorders with several high-acuity etiologies)." (PMID 31664120, 2019). "In turn, TLR3-induced IL6 was shown to trigger the upregulation of C-reactive protein (CRP), a potent pro-inflammatory cytokine commonly found at higher levels in patients with a neurological disorder." (PMID 36839434, 2023). "On the contrary, neurological presentations were inversely associated with markers of disease severity such as IL-6, TNF-α, IL-10/CXCL10, CRP, D-dimer, and LDH, all of which were significantly lower in patients with neurological diseases." (PMID 36851766, 2023). "We examined the localization of CRP in ALS-CP compared to neurological (AD) and non-neurological disease controls." (PMID 32586411, 2020). "We retrospectively determined the concentrations of CRP and PCT in the sera of patients consecutively enrolled from 2012 to 2015 in an etiological study on neurological disorders at the rural hospital of Mosango, Democratic Republic of Congo." (PMID 31664120, 2019). "Serum IL-6, LDH, ferritin, hs-troponin I, CRP, procalcitonin, and D-dimers measured within 6 h of hospital admission for neurological disorder were analyzed and compared between survivors and non-survivors." (PMID 41751490, 2026).
neurological diseases (continued). "Interestingly, in the entire study cohort, as well as in the controls without neurological diseases, CRP levels correlated positively with chemerin levels in serum." (PMID 39595074, 2024). "Therefore, this locus may not be an effective instrumental variable for CRP, and it is even more likely to be relevant to the outcome (especially lipid-related and neurological diseases) rather than the exposure." (PMID 34386016, 2021).
connective tissue diseases (47 papers, 2009 to 2026). "In other conditions involving ILDs, such as those related to radiation treatment or associated with connective tissue diseases, CRP or ESR levels were correlated with serum KL-6 in predicting disease severity." (PMID 40547914, 2025). "For example, high ESR/low CRP discordance is frequently observed in women, likely associated with their propensity to develop connective tissue disorders as reported by some studies." (PMID 31871540, 2019). "C-reactive protein (CRP) has been well studied in association with cardiovascular risk and is commonly used in practice by rheumatologists as a marker of inflammation in numerous connective tissue disorders." (PMID 41002646, 2025). "Indeed, ESR and CRP have emerged as risk factors for ILD in connective tissue diseases, including SSc." (PMID 40658121, 2025). "Viral swabs and a range of blood tests (full blood count, haematinics, haemoglobin A1c [HbA1c], connective tissue disease screen, anti-tTG, renal and liver profiles, CRP) were carried out." (PMID 39394298, 2024). "Reactive C protein (CRP) increases in acute inflammatory conditions such as infectious diseases and connective tissue diseases." (PMID 35178206, 2022). "Increased NLR values can be used as a marker similar to CRP in determining extensive inflammation in patients with connective tissue diseases because an increase in CRP may occur late during the evolution of the disease compared to NLR increase." (PMID 32751302, 2020). "However, she did have persistent immunologic reactivity and persistent elevation of her ESR and CRP; it is possible that she has an undifferentiated connective tissue disease." (PMID 26425609, 2014). "Her high ESR, high CRP, positive RF level, positive ANA, positive anti-SS-A, and positive anti-RNP antibodies suggest that a connective tissue disorder might explain her disease." (PMID 26425609, 2014). "Additionally, CRP represents a non-specific marker of inflammation and might have been influenced by various conditions or factors including infections, inflammatory diseases, connective tissue disorders, severe stress, and medical treatments which we could not account for in this study." (PMID 32182693, 2020).
retinopathy (42 papers, 2007 to 2026). "Despite extensive evidence indicating a link between inflammation and diabetic retinopathy, the data in the literature in regard to the association between CRP and retinopathy are controversial." (PMID 33239667, 2020). "There are several biologically plausible pathways by which CRP could be associated with the neurodegeneration and capillary dropout seen in retinopathy." (PMID 41159344, 2025). "CRP a well-established inflammatory biomarker, has been strongly associated with retinopathy." (PMID 40151349, 2025). "First, prospective cohort studies are needed to establish the causal and dynamic relationship between the albumin-lymphocyte-CRP factor and the progression of retinopathy." (PMID 40151349, 2025). "In sum, by amplifying NF-κB–driven inflammation and oxidative stress, CRP plausibly accelerates the neurodegeneration and capillary dropout seen in retinopathy." (PMID 41159344, 2025). "Although the CRP value for the retinopathy patients was approximately 6 points higher than the healthy controls, the difference was not statistically significant." (PMID 28616394, 2017). "After log transformation, we found a significantly higher CRP value for the retinopathy patients compared to the healthy subjects." (PMID 28616394, 2017). "Patients with ACR > 300 mg/g have higher percentage of grade II-IV retinopathy, serum uric acid level, total cholesterol, low density lipoprotein cholesterol, triglycerides and C-reactive protein than those with ACR ≤ 300 mg/g." (PMID 28828178, 2016). "At the beginning of the study, they found that there was a significant relationship between the grades of retinopathy and CRP." (PMID 26636823, 2015). "Different from that, isolated retinopathy were more likely to have lower level of CRP, which was consistent with the data from the Singapore Malay Eye Study." (PMID 24835219, 2014). "We can only demonstrate that higher hs-CRP coexists with more severe DR, not that CRP elevation precedes or causes retinopathy." (PMID 41159344, 2025). "Some authors have proposed CRP as a non-invasive systemic biomarker of retinopathy." (PMID 41159344, 2025). "Clinical trials of anti-inflammatory or CRP-lowering therapies (for instance, IL-6 receptor antagonists, statins, or novel CRP inhibitors) with DR endpoints would test whether dampening systemic inflammation can slow retinopathy." (PMID 41159344, 2025). "Currently, biomarkers commonly used for retinopathy risk prediction include traditional markers such as HbA1c and blood pressure, as well as emerging biomarkers such as neutrophil-lymphocyte ratio (NLR), monocyte-lymphocyte ratio (MLR), and C-reactive protein (CRP) and so on." (PMID 40151349, 2025). "In addition, IL-12 was found to be involved in the progression of retinopathy and CRP may upregulate its synthesis, which is in agreement with our results." (PMID 24677179, 2014). "The NPDR children demonstrated a significantly longer duration of the disease in addition to higherHbA1c, albumin excretion rate, C-reactive protein, as well as systolic blood pressure than those without retinopathy." (PMID 17641733, 2007). "However, when each of the parameters were assessed individually (partial correlation), the correlation of total cholesterol and C-reactive protein with retinopathy were no longer significant." (PMID 28828178, 2016). "However, the patients with T1DM and without retinopathy had significantly higher serum levels of HbA1c and CRP, higher urinary albumin excretion, and higher systolic blood pressure values in comparison with the control group (P < 0.05)." (PMID 23671881, 2013). "Baseline characteristics also revealed that participants in the retinopathy group had lower BMI and HDL levels, but higher CRP levels compared to those in the non-retinopathy group." (PMID 40151349, 2025).
retinopathy (continued). "The NPDR children demonstrated a significantly longer duration of the disease in addition to higher HbA1c, albumin excretion rate, C-reactive protein, systolic blood pressure, as well as TNF-α and IL-6 levels than those without retinopathy." (PMID 17641733, 2007). "In relation to those without retinopathy, the NPDR children demonstratedsignificantly longer duration of the disease, they had higher HbA1c, urine albumin excretion rate,CRP level, as well as the systolic blood pressure." (PMID 17641733, 2007). "However, body mass index, blood pressure indices, C-reactive protein and ACR were similar between patients with and without retinopathy." (PMID 28828178, 2016).
adenocarcinoma (29 papers, 2011 to 2025). A common cancer characterized by the presence of malignant glandular cells. "At univariate analysis, predictors of worse survivals were increasing age at surgery, lower BMI, weight loss, higher baseline C-reactive protein, pathological stage, and, among patients with adenocarcinoma, higher grade." (PMID 35205621, 2022). "CRP mRNA high expression was significantly associated with worse survival in adenocarcinoma patients (HR, 1.41 (1.12–1.78), P=0.0032)." (PMID 31142628, 2019). "While sTNFR1 and CRP had prognostic value for both squamous and adenocarcinoma, some proteins showed histology-dependent association with survival." (PMID 30005623, 2018). "Similarly, the C-reactive protein–ALB ratio is strongly associated with poor prognosis in patients with adenocarcinoma of the esophagogastric junction and upper GC." (PMID 40601671, 2025). "At univariate analysis, predictors of worse survivals were: increasing age at surgery (p = 0.0042), lower BMI (p = 0.009), weight loss (p = 0.0034), higher CRP (p = 0.049), pathological stage (p = 0.00000042), and, among patients with adenocarcinoma, higher grade (p = 0.028)." (PMID 35205621, 2022). "Prothrombin activity showed a significant correlation with C-reactive protein (CRP) in non-adenocarcinoma patients, highlighting a possible link between coagulation and systemic inflammation." (PMID 40332145, 2025). "In patients with adenocarcinoma, the level of C-reactive protein (CRP) was significantly influenced by a combination of clinical and laboratory parameters." (PMID 40332145, 2025). "A statistically significant correlation was identified between prothrombin activity and C-reactive protein in the non-adenocarcinoma group, suggesting a possible link between coagulation function and systemic inflammation in these patients." (PMID 40332145, 2025). "The best markers for differentiating adenocarcinoma from SqCC are glucose (AUC = 0.674), CRP (AUC = 0.612), and CYFRA 21-1 (AUC = 0.609), and there are no significant variations in their utility when corrected for age and gender." (PMID 34439874, 2021). "In adenocarcinomas, level of sTNFR1 and CRP had a significant impact on progression free survival." (PMID 30005623, 2018). "High CRP levels correlated with male gender, ≥20 pack years, Stage III‐IV, histology other than adenocarcinoma, and ECOG score ≥2." (PMID 37329173, 2023). "Glucose with AUC = 0.674, CRP with AUC = 0.612, and CYFRA 21-1 with AUC = 0.609 can identify SqCC from adenocarcinoma patients." (PMID 34439874, 2021). "VEGFR2 is significantly higher expressed in non-malignant lung tissue in all patient subsets except for adenocarcinoma, CRP ≤ 5 mg/L, no COPD and women." (PMID 30016964, 2018).
gastrointestinal tumors (21 papers, 1983 to 2024). "Elevated levels of CRP have been described as a prognostic factor in various human malignancies, including tumors of the digestive system." (PMID 26848624, 2016). "GPS is an inflammation biomarker based on CRP and ALB, which has been shown highly discussed in gastrointestinal tumors including ESCC before." (PMID 34315926, 2021). "In addition, there has been controversy regarding the value of CRP and PCT in predicting postoperative infectious complications in gastrointestinal tumors." (PMID 38504206, 2024).
peripheral neuropathy (19 papers, 2014 to 2025). A disorder affecting the peripheral nervous system. "ADRs that occurred at more than a 2-fold higher rate in patients aged ≥65 years than those aged <65 years were febrile neutropenia for all grade ADRs, and febrile neutropenia, peripheral neuropathy, and C-reactive protein increased for ADRs of Grade ≥3." (PMID 35546669, 2022). "Results were adjusted for age, gender, race-ethnicity, comorbidity index, smoking, HgbA1C, C-reactive protein, homocysteine, glomerular filtration rate, microalbuminuria, peripheral neuropathy, physical functioning, and medication use." (PMID 24967220, 2014). "In 1 of these excluded cases, the observed adverse events included lower extremity peripheral neuropathy, high cholesterol, cracked skin on the hands, reduced magnesium, chills, fever, elevated CRP level, slightly elevated white blood cell count, and reduced pre-albumin level." (PMID 35949598, 2022). "CRP concentrations, as a systemic marker of inflammation, were linked to physical capacity but not directly to peripheral neuropathy." (PMID 31959163, 2020). "However, when evaluated, discrimination was linked to each outcome examined including worse sleep, higher levels of pain, higher blood pressure, higher prevalence of coronary calcium, greater IMT, higher probability of having peripheral neuropathy, and higher CRP levels." (PMID 35130984, 2022). "The nomogram incorporated age, C-reactive protein (CRP), Wagner grade, lower extremity arterial disease (LEAD), and peripheral neuropathy (PN)." (PMID 40604114, 2025). "In this study, our data clearly demonstrated behavioral, biochemical (CRP), hematological, and histopathological alternations in CCI animals due to the induction of peripheral neuropathy in mice." (PMID 31341489, 2019). "There are also no experimental studies that have examined any correlation between CRP and ESR in animal models of peripheral neuropathy." (PMID 31341489, 2019). "The levels of C-reactive protein (CRP) in those SJS patients with or without peripheral neuropathy were 1.6 (0.75–3.2) and 2.7 (1.2–11.1) (ng/L), respectively (P = 0.181)." (PMID 24822219, 2014).